CX3CL1 (C-X3-C motif chemokine ligand 1)
Diseases named in the same sentence as CX3CL1 in open-access papers (continued):
Sharing a sentence is not in itself a finding about the gene and the disease.
diabetes (34 papers, 2011 to 2026). "On the other hand, CX3CL1 was positively associated with diabetes exclusively in men with African ancestry." (PMID 35365620, 2022). "Another meta-analysis also supports the association between heightened CX3CL1 concentration and the onset of T2D, indicating that CX3CL1 may contribute to the pathogenesis of diabetes through inflammation and immune response." (PMID 38606083, 2024). "The increased risk remained significant for KIM-1, UPAR, MMP12, cathepsin L1, TNFR2, and CX3CL1 after adjustments for cardiovascular risk factors (i.e., diabetes, systolic blood pressure, blood lipids, use of blood pressure or lipid-lowering medications and waist circumference)." (PMID 31114450, 2019). "Fractalkine (CX3CL1) exists in both a soluble and transmembrane form, and plays a role in both immune cell migration and adhesion and has been implicated in multiple inflammatory diseases such as asthma, dermatitis, diabetes, and neuropathic pain." (PMID 30150990, 2018). "Olink proteomic profiling revealed that SZF treatment markedly downregulated CX3CL1 and MCP-1, both of which are closely associated with renal inflammation and fibrotic progression in diabetes." (PMID 41393243, 2025). "Fractalkine (CX3CL1) is expressed by various cells, contributing to the pathogenesis of diseases such as diabetes mellitus, vascular pathologies, and rheumatoid arthritis via immunological mechanisms." (PMID 41337567, 2025). "Recent research highlights CX3CL1 as a novel adipokine regulated by obesity and diabetes, potentially contributing to low-grade inflammation in adipose tissue linked to these conditions." (PMID 40542047, 2025). "The prevalence of diabetes mellitus (DM) was significantly higher in the high CX3CL1 group in an adjusted model in a study of prospectively collected serum samples from CKD patients." (PMID 40508161, 2025). "Except kidney and heart, there are many tissues in diabetes that express CX3CL1 such as adipose, brain, and so on." (PMID 35370759, 2022). "Elevated circulating levels of CX3CL1 were detected in patients with type 2 DM, suggesting a link between CX3CL1 and diabetes." (PMID 35370759, 2022). "Treatment of mesangial cells with CX3CL1 or with other diabetes-related stimuli also induced higher expression of the pro-fibrotic molecules TGF-β, collagen 4α1 and fibronectin at both mRNA and protein levels." (PMID 34163473, 2021). "CX3CL1 displays pro-angiogenic and pro-inflammatory effects in a number of pathological conditions, including rheumatoid arthritis, diabetes, and cancers." (PMID 30845779, 2019). "Little is known regarding monocyte phenotype or CX3CR1 expression and diabetes, although it has been shown that monocytes display an activated phenotype in diabetics and the production of CX3CL1, likely by adipocytes, is found at higher levels in diabetics." (PMID 25105870, 2014). "In contrast, the proinflammatory background of diabetes, which includes increased placental levels of TNFα, IFNγ, and IL-1β, promotes enhanced CX3CL1 gene expression." (PMID 23956503, 2013). "In this study we examined comparatively (diabetes class C complicated versus normal pregnancy) the correlation between CX3CL1 content in placental tissue, the mean CX3CR1 expression, and density of the network of placental microvessels." (PMID 23956503, 2013). "In conclusion, we suggest involvement of CX3CL1/CX3CR1 signaling pathway in the pathomechanism of placental microvasculature remodeling in diabetes class C." (PMID 23956503, 2013). "The mean concentration of CX3CL1 in diabetes was increased and accompanied by augmented placental microvessel density as well as a higher expression of CX3CR1." (PMID 23956503, 2013). "The aim of this study was to examine comparatively (diabetes class C—complicated versus normal pregnancy) the correlation between CX3CL1 content in placental tissue, the mean CX3CR1 expression, and density of the network of placental microvessels." (PMID 23956503, 2013).
diabetes (continued). "Further studies are needed to determine which mechanism of CX3CL1 regulation predominates in diabetes class C." (PMID 23956503, 2013). "In conclusion, it is very likely that increased CX3CL1 concentration in diabetes class C, together with the upregulation of its specific and sole receptor, CX3CR1, are involved in the pathomechanism of placental microvasculature remodeling." (PMID 23956503, 2013). "Our research indicates that CX3CL1 contributes to the initial onset of type 2 diabetes but exerts an insubstantial effect on the progressive complications of T2D, providing support for the prevention and early intervention of diabetes." (PMID 38606083, 2024). "Several studies have shown that CX3CR1 and CX3CL1 are upregulated in the kidneys of patients with diabetes, accompanied by an increase in urea, creatinine, A/C ratio, HbA1C, and IgG; however, the concrete mechanism of CX3CL1-CX3CR1 recruiting T cells requires further exploration in DKD." (PMID 36776877, 2023). "Accordingly, inhibition of the CX3CL1/CX3CR1 system by neutralizing antibody of CX3CL1 or silencing of CX3CR1 or SGLT2i may represent a novel therapeutic strategy for improving cardiorenal dysfunction in diabetes." (PMID 35370759, 2022). "Taken together, it seems that CX3CL1/CX3CR1 system may play an important role in cardiorenal crosstalk via circulating sCX3CL1 in diabetes." (PMID 35370759, 2022). "Here we attempt to clarify whether CX3CL1 might be a therapeutic target for cardiorenal dysfunction in diabetes." (PMID 35370759, 2022). "Furthermore, some studies in animal models also report that fractalkine or CX3CL1, a (C-X3-C motif) chemokine, is expressed at early stages of diabetes in both cardiomyocytes and cardiac fibroblasts (in addition to MCP-1)." (PMID 31284374, 2019). "The potential role of CX3CL1 in the pathogenesis of diabetes mellitus has emerged more recently." (PMID 26393344, 2015). "This shift may influence the placental cytokine network profile in diabetes, possibly including an increase in the local CX3CL1 concentration." (PMID 23956503, 2013). "The results of the present investigation strongly support the hypothesis that CX3CL1-related pathways is involved in the pathomechanism of placental angiogenesis in diabetes." (PMID 23956503, 2013). "With a 41% increased dementia risk by 1 SD increase of either CX3CL1 or EN-RAGE levels, the associations of these two inflammatory biomarkers with dementia were stronger than the associations of male sex, education, CVD, and diabetes with all-cause dementia in our cohort." (PMID 36085081, 2022). "Thus, extracellular matrix degradation may be reduced in diabetes due, in part, to increased CX3CL1 expression and this may contribute to renal extracellular matrix deposition and progression of renal impairment in DN." (PMID 34163473, 2021). "The potential to target the CX3CL1/CX3CR1 axis via therapeutic intervention at the level of the placenta in PE- and diabetes-complicated pregnancy is the subject of ongoing research." (PMID 41683599, 2026). "Under the chemotaxis of chemokines (CCL2, CX3CL1, CCL5, etc.), phagocytes such as monocytes and macrophages gather at the site of diabetes complications." (PMID 36755923, 2023). "Human aortic smooth muscle cells (SMCs) exposed to a high concentration of glucose increase monocyte–SMC adhesion interactions by upregulating CX3CL1 and MCP-1 expression, thereby exacerbating vascular inflammation in patients with diabetes mellitus." (PMID 35735031, 2022). "Treatment with the ACE-inhibitor temocapril reduced intra-renal mRNA and protein levels of CX3CL1 and CX3CR1 eight weeks after induction of diabetes." (PMID 34163473, 2021). "Indeed, at 50 ng/mL, an up-regulation was only observed for IFNγ in response to the diabetes and CAD marker IL-18, but a reduction for at least one of the three T-cell activity markers in response to all other biomarkers except CX3CL1 and periostin." (PMID 34281240, 2021).
diabetes (continued). "This study did not involve women with diabetes class C, and CX3CL1 concentrations were not examined." (PMID 23956503, 2013). "We reported that circulating CX3CL1 levels were higher in subjects with diabetes than without." (PMID 26393344, 2015). "In this study, we investigated the potential role of CX3CL1 in cardiorenal dysfunction by using streptozotocin (STZ)-induced DM or spontaneously diabetic mice (non-obese diabetes, NOD)." (PMID 35370759, 2022).
glioma (33 papers, 2014 to 2025). A benign or malignant brain and spinal cord tumor that arises from glial cells (astrocytes, oligodendrocytes, ependymal cells). "In parallel, MG highly expressing Cx3cr1 are led towards glioma by Cx3cl1, which is secreted by glioma cells with NF1 mutation." (PMID 34671362, 2021). "More specifically, studies have shown that the CX3CL1/CX3CR1 axis is overexpressed in invading glioma cells, and when treated with neutralizing antibodies, this invasiveness is largely reduced." (PMID 38893093, 2024). "Studies have shown that mutation in the IDH1 gene, especially the R132H mutation, can promote NK cell recruitment through CX3CL1/CX3CR1 chemotherapy and are associated with a better prognosis in gliomas." (PMID 35601497, 2022). "The use of a neutralizing mAb to block endogenous CX3CL1 function dramatically slowed tumor cell aggregation and boosted glioma invasiveness." (PMID 35269652, 2022). "It has been reported that neurons express chemokine CX3CL1 to recruit CX3CR1+ NKs to the brain parenchyma, which is associated with a better prognosis against e.g. glioma." (PMID 35185929, 2022). "NK cells are present within the glioma tumor microenvironment and are attracted towards the tumor by neuronal expressed chemokine CX3CL1." (PMID 35185929, 2022). "Several chemokines and cytokines, including CCL2 and CX3CL1, are responsible for GAMs recruitments and expansion in glioma." (PMID 34084145, 2021). "Analysis based on The Cancer Genome Atlas (TCGA) and the Chinese Glioma Genome Atlas (CGGA) databases showed that high levels of CX3CL1 positively correlate with patient OS in glioma." (PMID 34203660, 2021). "These glioma-associated microglia and MΦ (GAM) are recruited by glioma cells, secreting several chemoattractants such as CCL2, Cx3CL1, SDF-1, and CSF-1, among others." (PMID 34445160, 2021). "Inhibition of endogenous CX3CL1 using a neutralizing monoclonal antibody resulted in marked latency of tumor cell aggregation and increased glioma invasiveness." (PMID 32456359, 2020). "Accumulation of soluble CX3CL1 was observed in the supernatants from glioma cell lines, indicating that the chemokine is constitutively released also by these tumors." (PMID 32456359, 2020). "Even if CCL2 is believed to be the major recruiter of TAMs in gliomas, other factors like CX3CL1, CXCL12, M-CSF and GM-CSF can mobilize TAMs into brain tumor areas, and become relevant under Ccr2-deficiency." (PMID 32668709, 2020). "The CX3CL1 chemokine (also known as fractalkine) produced by neurons mediates CX3CR1+ NK cell recruitment to the brain and is associated with a favorable glioma prognosis." (PMID 32903717, 2020). "In the context of glioma, CXCL12/CXCL12-receptor (CXCR4/CXCR7) autoregulatory signaling has been demonstrated to be important for glioblastoma survival and angiogenesis, while CX3CL1/CX3CR1 axis signaling in glioma cells controls glioma cell invasion." (PMID 28380429, 2017). "Here, we show that loss of CX3CR1/CX3CL1 signaling in tumor-associated microglia and monocytes results in an increased incidence of GBM formation with shorter tumor latency in glioma-bearing mice." (PMID 25987130, 2015). "In this study we abrogated CX3CR1/CX3CL1 signaling in both microglia and inflammatory monocytes and studied the effects on glioma growth and on the behavior of both cell populations." (PMID 25987130, 2015). "Treatment of glioma cells with recombinant transforming growth factor (TGF)-beta 1 reduced CX3CL1 expression at mRNA level, facilitating glioma cell detachment and dispersion." (PMID 24799766, 2014). "CX3CL1 negatively regulates glioma cell invasiveness by promoting tumor cell aggregation when expressed as transmembrane protein." (PMID 24799766, 2014). "CX3CL1, a vital chemokine family member, has a negative regulatory role on glioma cells." (PMID 38530810, 2024). "Interestingly, in IDH1-mutant gliomas, 2-HG can activate NF-κB, regulate CX3CL1 expression, and then CX3CL1 recruits NK cells to the tumor location." (PMID 35769466, 2022).
glioma (continued). "In addition to that, blocking CX3CL1 with a monoclonal antibody increased glioma cell invasion and reduced tumor cell aggregation." (PMID 34203660, 2021). "Furthermore, CX3CL1 expression correlates with glioma grade and serves as a prognostic marker for glioma patient OS." (PMID 34203660, 2021). "Moreover, the expression of CX3CL1 in glioma cell lines, both on mRNA and protein level, was decreased by the treatment with TGF-β, a key regulator of glioma cell invasiveness." (PMID 32456359, 2020). "Furthermore, stimulation with s-CXCL16 and s-CX3CL1 reduced caspase-3/7 activity that was induced by exposure to Temozolomide, a clinically used chemotherapeutic for gliomas." (PMID 26796342, 2016). "Thus, a reduction of GATA3 expression may be involved in CXCL16-regulated or CX3CL1-regulated inhibition of THSD4 expression in gliomas." (PMID 32346064, 2020). "In the glioma microenvironment, microglia can be recruited by gliomas through chemoattractants such as CCL5, CCL2, CX3CL1, and CXCL12, and can penetrate the tumor." (PMID 38549161, 2024). "While CX3CL1 and its receptor CX3CR1 are low expressed in cluster B, which have been proven to negatively regulate glioma invasiveness." (PMID 38181024, 2024). "The CX3CL1 expression was inversely correlated with overall patient survival, and this increased expression of grades III-IV gliomas suggests that this axis is involved in the tumor’s malignant behavior." (PMID 35269652, 2022). "Monocyte chemotactic protein 1 (MCP-1, CCL2) secreted by glioma cells mediated the recruitment of CCR2+ monocytes and macrophages, and CX3CL1 induced the infiltration of CX3CR+ microglia." (PMID 34211978, 2021). "As a special member of glioma TME, microglia are recruited to lesions through CX3CL1/CX3CR1 chemokine channel, while peripheral monocyte-macrophages through the MCP-1/CCR2 channel." (PMID 34211978, 2021). "CX3CL1 and CX3CR1 constitute the next chemokine ligand/receptor axis that plays an important role in glioma development." (PMID 32456359, 2020). "Glioma cells release chemo-attractans, such as monocyte chemo-attractant protein-1 (MCP-1), fractalkine (CX3CL1), glial cell–derived neurotrophic factor (GDNF), and colony stimulating factor-1 (CSF)-1) that recruit GAMs to tumor tissue." (PMID 31467533, 2019). "Nonetheless, gliomas are also known to secrete chemoattractant molecules (e.g., CSF1, SDF1, CX3CL1) that attract microglia/macrophages." (PMID 28098415, 2017). "To study the functional role of CX3CR1/CX3CL1 signaling in GBM, we used a genetically engineered mouse model (GEMM) of adult PDGFB-driven gliomas, which is based on RCAS/Tv-a, a somatic cell-specific gene transfer system." (PMID 25987130, 2015). "Recently, expression and function of CX3CL1 and CX3CR1 have been demonstrated in glioma tumors irrespectively of their histotype and clinical severity." (PMID 24799766, 2014). "However, their report primarily centered around the expression of the chemokine CX3CL1, which was the only chemokine with increased expression in IDH‐mutant glioma in comparison to IDH‐wildtype." (PMID 38339779, 2024). "CX3CL1 and CX3CR1 have a positive immunological expression on tumor cell membranes, and soluble CX3CL1 accumulates in cell culture supernatants, indicating that gliomas produce this chemokine on a regular basis." (PMID 35269652, 2022). "Glioma cells express both CX3CR1 and CX3CL1 at mRNA and protein levels." (PMID 34203660, 2021). "Furthermore, analysis of CX3CL1 and CX3CR1 expression in human glioma surgical samples with different histological degrees demonstrated that both ligand and receptor were present in most specimens, at the mRNA and protein levels." (PMID 32456359, 2020). "MAPK3 and CX3CL1 were strongly positive; NFE2L2, HSP90AB1, and SUPT20H were moderately positive; and FKBP1B, BIRC5, NPC1, IKBKE, BID, and PTEN were weakly positive in glioma tissue relative to their expression levels in normal tissue." (PMID 33194668, 2020).
glioma (continued). "A viral encoded putative receptor for CX3CL1, US28, was detected neither in glioma cells, nor in LOX melanoma cells, and thus, can be excluded for s-CXCL16 or s-CX3CL1 signaling." (PMID 26796342, 2016). "Both chemokines, s-CXCL16 and s-CX3CL1, significantly enhanced proliferation of classical receptor-negative, tm-chemokine-positive cells like U343 or A764 glioma cells, whereas double-negative cells like LOX melanoma cells did not respond." (PMID 26796342, 2016). "However, the representative chemokines in glioma (CXCL12, CXCL16, CX3CL1, CCL2) were not significantly correlated with poor OS in the same database." (PMID 34638384, 2021).